KIAA1328 (KIAA1328)
Description:
Competes with SMC1 for binding to SMC3. May affect the availability of SMC3 to engage in the formation of multimeric protein complexes.
Tractability: Antibody: the Human Protein Atlas places it where antibodies can reach. PROTAC: ubiquitination databases record sites on it.
Gene: Protein-coding gene on chromosome 18 (36,828,982 to 37,232,172, forward strand). Ensembl gene ENSG00000150477.
Subcellular location (Human Protein Atlas): Nuclear speckles; Lipid droplets; Plasma membrane; Vesicles
Gene Ontology:
Molecular function: protein binding
Genetic constraint (gnomAD): Loss-of-function variants: 42 observed, 49.87 expected, observed/expected ratio (o/e) 0.84, 90% interval 0.66 to 1.09. The upper end of that interval is the gene's LOEUF score, 1.09, which puts it in group 4 of 6, group 1 being the genes least tolerant of losing a copy. Missense variants: 561 observed, 577.57 expected, observed/expected ratio (o/e) 0.97, 90% interval 0.91 to 1.04. Synonymous variants: 192 observed, 205.69 expected, observed/expected ratio (o/e) 0.93, 90% interval 0.83 to 1.05.
Homologues: Orthologues: chimpanzee KIAA1328 (99% identical), macaque KIAA1328 (94% identical), dog KIAA1328 (78% identical), rabbit KIAA1328 (77% identical), pig KIAA1328 (76% identical), mouse AW554918 (73% identical), rat Kiaa1328 (72% identical).
Diseases named in the same sentence as KIAA1328 in open-access papers:
KIAA1328 is named in the same sentence as 2 diseases in open-access papers, as found by Europe PMC text mining. Sharing a sentence is not in itself a finding about the gene and the disease. The quoted sentences say what the papers report.
small bowel cancer (1 paper, 2022). "Neither KIAA1328 nor CELF4 have previously been implicated in small bowel cancer." (PMID 35922826, 2022).
KIAA1328 also shares sentences with these, for which no sentence is quoted: ciliopathy (1 paper).